HGF (hepatocyte growth factor)
Diseases named in the same sentence as HGF in open-access papers (continued):
Sharing a sentence is not in itself a finding about the gene and the disease.
malignant glioma (9 papers, 2005 to 2021). A grade III or grade IV glioma arising from the central nervous system. "Here, we used V-4084, a small molecule compound that selectively inhibits MET kinase activity (Ki = 0.025 μM), to further test inhibition of HGF-autocrine-dependent GBM invasion using U87MG malignant glioma cells." (PMID 26381735, 2015). "Several studies have revealed that the macrophage chemoattractant protein-1 (MCP-1) and hepatocyte growth factor (HGF) are able to promote MSC migration into malignant gliomas, confirming the potential applications of genetically modified MSCs for cancer gene therapy." (PMID 24626964, 2014). "Hepatocyte growth factor (HGF) and BCL-2 family proteins promote invasion via TGF-beta and activity of matrix metalloproteinase (MMP) in human malignant glioma cells using a furin-dependent pathway." (PMID 31382374, 2019). "Malignant gliomas contain large quantities of VEGF, PDGF, bFGF and HGF, as well as their receptors; their concentrations are related to vascular density, radioresistance, cell proliferation, degree of malignancy and patient́s survival." (PMID 15785746, 2005). "Signaling through the HGF/c-Met pathway was reported to trigger the upregulation and secretion of the pro-angiogenic VEGF in malignant glioma cells thereby inducing the proliferation of neuromicrovascular endothelial cells within the brain cancers via a paracrine and autocrine loop signaling." (PMID 34055785, 2021). "With respect to radiation-induced EMT, it has been repeatedly shown that treating malignant glioma cells with sub-lethal doses of radiation in vitro significantly enhances tumor cell motility through upregulation of TGF-β, HGF/c-MET, and vascular endothelial growth factor (VEGF) signaling." (PMID 28821904, 2018).
oral squamous cell carcinoma (9 papers, 2019 to 2025). "Identification of prognostic genes in the oral squamous cell carcinoma (OSCC) microenvironment revealed that HGF expression significantly correlates with the infiltration levels of B cells, CD4+T cells, CD8+T cells, macrophages, and neutrophils." (PMID 40823073, 2025). "In oral squamous cell carcinoma cell lines, upregulated Lpd induced by hepatocyte growth factor/c-Met signaling also promotes oral squamous cell carcinoma cell migration." (PMID 41360259, 2025). "HGF released from stromal fibroblasts was found to play a role in the invasion of oral squamous cell carcinoma cells in early investigations, and further research found that neutralizing HGF inhibited cancer cell invasiveness." (PMID 35630066, 2022). "In the early 1990s, the first studies of HGF in cancer demonstrated the invasive properties of HGF through co-culture experiments of stromal fibroblasts and human oral squamous cell carcinoma." (PMID 33066121, 2020). "HGF upregulates ETV5 to promote cell invasion of oral squamous cell carcinoma." (PMID 36109787, 2022). "In oral squamous cell carcinoma (OSCC), hepatocyte growth factor (HGF) was expressed in CAFs and regulated lymphangiogenesis by binding to the c‐Met receptor in OSCC." (PMID 35832030, 2023). "We used immunohistochemistry to investigate HGF and c-Met expression in 53 oral squamous cell carcinoma (OSCC) specimens and 21 adjacent nontumor specimens and evaluated the associations between HGF and c-Met expression and clinicopathological parameters." (PMID 34970484, 2021).
pancreatic ductal adenocarcinoma (9 papers, 2018 to 2024). An infiltrating adenocarcinoma that arises from the epithelial cells of the pancreas. "FOXM1 binds to the Met gene promoter and enhances HGF/Met signaling in pancreatic ductal adenocarcinoma cells by transcriptionally increasing Met expression." (PMID 36591565, 2022). "Indeed, LECT2 was found to suppress tumor metastasis by targeting the HGF/c-Met signaling in pancreatic ductal adenocarcinoma (PDAC)." (PMID 38177412, 2024). "In preclinical pancreatic ductal adenocarcinoma (PDAC) models, inhibition of hepatocyte growth factor (HGF) signaling using ficlatuzumab, a recombinant humanized anti-HGF antibody, and gemcitabine reduced tumor burden." (PMID 36807743, 2023). "In addition, the HGF-MET axis regulates mTOR activity and controls serum starvation-mediated autophagy and biogenesis In pancreatic ductal adenocarcinoma, several studies have reported that MET promotes malignant phenotypes and contributes to tumor growth." (PMID 34956177, 2021). "Furthermore, HGF-c-MET signaling also leads to activation of the PI3K/AKT pathway and AKT1 has been identified as a direct target of hsa-miR-637 in pancreatic ductal adenocarcinoma cells." (PMID 31063487, 2019). "MiR-7-5p acts as a tumor suppressor in pancreatic ductal adenocarcinoma and suppresses cell proliferation, migration and invasion by targeting SOX18; in MCF-10A mammary epithelial cells, this miRNA suppresses oncogenes by mediating the signaling of hepatocyte growth factor." (PMID 30993031, 2019).
sarcopenia (9 papers, 2016 to 2026). Progressive decline in muscle mass due to aging which results in decreased functional capacity of muscles. "Several inflammatory cytokines, such as CD6, HGF, and IL-7, have demonstrated suggestive associations with sarcopenia-related traits." (PMID 39193020, 2024). "In this study, we employed MR analysis to provide a more holistic perspective on the causal relationship between inflammatory cytokines and sarcopenia, suggesting that elevated levels of IL-7, MCP-3, RANTES, and IL-1RA increase, whereas HGF, IP-10, and M-CSF decrease the risk of sarcopenia." (PMID 39345889, 2024). "In addition to these experimental studies, a few clinical observational studies have proposed a relationship between sarcopenia and HGF." (PMID 39345889, 2024). "The effects of HGF on sarcopenia have been reported by experimental studies." (PMID 39229276, 2024). "Overall, findings highlight inhibitory impacts of HGF nitration on myogenic stem cell dynamics, pioneering a cogent discussion for better understanding age‐related muscle atrophy and impaired regeneration with fibrosis (including sarcopenia and frailty)." (PMID 37985931, 2024). "Thus sustained systemic levels of HGF may constitute a link between immunosenescence and sarcopenia, although further studies are needed to investigate this relationship." (PMID 27545843, 2016).
acute respiratory distress syndrome (8 papers, 2005 to 2025). Progressive and life-threatening pulmonary distress in the absence of an underlying pulmonary condition, usually following major trauma or surgery. "A two-sample Mendelian randomization (MR) analysis was conducted to assess the causal relationship between hepatocyte growth factor (HGF) and acute respiratory distress syndrome (ARDS)." (PMID 40799816, 2025). "For example, HGF is detected exclusively in BALF from patients with sepsis-related acute respiratory distress syndrome (ARDS), and the elevation in HGF levels is evident in patients with severe, rather than mild, injury." (PMID 22536224, 2012). "For example, MSCs can suppress the inflammatory response by secreting HGF, IL-10, and TSG-6 in acute respiratory distress syndrome (ARDS) and COVID-19-associated pneumonia, thereby repairing the alveolar structure and reducing pulmonary edema." (PMID 39949625, 2025). "A study has previously shown that HGF is elevated in pulmonary fluid in acute lung injury (ALI) and acute respiratory distress syndrome (ARDS) and that higher HGF levels are associated with increased mortality." (PMID 21429184, 2011).
deafness (8 papers, 2014 to 2025). An inherited or acquired condition characterized by the complete loss of the ability to hear from one or both ears. "In this study, we performed targeted NGS in three Pakistani consanguineous families and identified novel variants in TECTA and POU3F4 and previously reported variants in MYO7A and HGF as the pathogenic causes for prelingual, severe-to-profound deafness." (PMID 33976695, 2021). "MAP3K1 phosphorylates serine and threonine and functions in a signaling pathway where pathogenic variants of HGF, MET, and GAB1 were previously reported to be associated with human deafness DFNB39, DFNB97, and DFNB26, respectively." (PMID 39062623, 2024). "As summarized above, in this study, rare pathogenic variants were identified in four separate deafness-associated genes, TECTA, MYO7A, HGF, and POU3F4, which have distinct expression profiles and functions in the inner ear." (PMID 33976695, 2021). "For example, a dominant variant of METTL13 (DFNM1) completely suppresses recessive non-syndromic deafness DFNB26, associated with a variant of GAB2 with both genes functioning in the HGF/MET signaling pathway." (PMID 32987832, 2020). "Researchers believe that the pharmacological effects of MET inhibitors can lead to an unstable HGF/c-MET signaling pathway, which may cause deafness in patients by disrupting the development of stria vascularis." (PMID 41411333, 2025). "Interestingly, in a large, multigenerational consanguineous family, we identified two separated variants in HGF and POU3F4, illustrating the complex genetic heterogeneity of deafness." (PMID 33976695, 2021). "Furthermore, a cKO model of HGF deregulation, in which HGF was deleted from a limited number of tissues including cochlea, was associated with extensive cochlear pathology with morphogenetic defects and non-progressive deafness." (PMID 34179015, 2021).
esophageal squamous cell carcinoma (8 papers, 2013 to 2022). Esophageal squamous cell carcinoma (ESCC) is a type of esophageal carcinoma (EC) that can affect any part of the esophagus, but is usually located in the upper or middle third. "Furthermore, it has been reported that higher HGF levels in serum and tissue are associated with tumor progression and poor survival in esophageal squamous cell carcinoma." (PMID 25885021, 2015). "Furthermore, it has been demonstrated that HGF significantly increases the migration and invasion of esophageal SCCs in vitro, and that it is a major component of tumor progression induced by tumor-associated fibroblasts." (PMID 24887580, 2014). "It was observed that in esophageal squamous cell carcinoma (ESCC), HGF-induced angiogenesis is driven by either pro-angiogenic cytokines (e.g., VEGF and IL-8) or independently of VEGF, through Akt and Erk activation in endothelial cells." (PMID 30352967, 2018). "Previous studies have suggested the involvement of c-Met and/or its ligand, hepatocyte growth factor (HGF), in esophageal squamous cell carcinoma (ESCC), but the correlation between c-Met status and clinical outcome remains unclear." (PMID 26036285, 2015).
Ewing sarcoma (8 papers, 2020 to 2025). A small round cell tumor that lacks morphologic, immunohistochemical, and electron microscopic evidence of neuroectodermal differentiation. "Preclinical findings suggest potential synergistic efficacy of a combination of HGF-targeted neutralizing antibodies with CAR-T cell treatments in Ewing sarcoma models." (PMID 40909947, 2025). "In a model of Ewing sarcoma, which is characterized by the aberrant expression of hepatocyte growth factor (HGF), AMG102, an HGF receptor neutralizing antibody, improved the antitumor activity of anti-GD2 CAR T cells by increasing CAR T cell trafficking into the tumor mass." (PMID 34209505, 2021). "Comparatively, GD2-directed CAR T-cells potentiated the effects of an HGF-neutralizing antibody, AMG102, in Ewing sarcoma cell lines." (PMID 40983796, 2025). "inadvertently discovered that hepatocyte growth factor (HGF) enhances GD2 expression on the surface of Ewing sarcoma cells and achieves unexpected anti-tumor effects when combined with GD2-CAR-T cells for the treatment of Ewing sarcoma." (PMID 39916962, 2024). "Moreover, in preclinical Ewing sarcoma models, GD2-specific CAR-T cells combined with HGF-targeted neutralizing antibody (AMG102) inhibited tumor growth and metastasis." (PMID 36824365, 2023).
ischemic disease (8 papers, 2013 to 2025). Lack of blood supply to an area of the body, resulting in impairment of tissue oxygenation. "While both factors promote angiogenesis, HGF stimulates vascular stability and has anti-inflammatory and anti-necrosis properties beneficial for treating ischemic diseases." (PMID 40822341, 2025). "According to previous studies, it is reported that the therapeutic efficiency of ischemic disease increases when several factors were injected together rater than single factors such as VEGF or HGF." (PMID 36100628, 2022). "Our results are supported by the studies by Hayashi and colleagues who demonstrated that hypoxic treatment of vascular cells downregulated HGF production due to decreased cAMP, consistent with their potential role in the pathophysiology of ischemic diseases." (PMID 27612459, 2016). "It is well accepted that MSCs exert therapeutic effects on ischemic diseases by directly producing or stimulating endogenous factors, such as vascular endothelial growth factor (VEGF), hepatocyte growth factor (HGF) and stromal-derived factor-1 (SDF-1)." (PMID 33396665, 2020). "Traditional cytokine-based therapies, including those that use VEGF, FGF, hepatocyte growth factor (HGF), and stromal cell-derived factor-1α, have shown theoretical and experimental promise for use in treating ischemic diseases." (PMID 28583178, 2017). "In the future, ADSCs infected with the recombinant human HGF lentiviral vector will be used to study the function of the target gene in combination with stem cells in IHD and other ischemic diseases." (PMID 23484149, 2013).
keloid (8 papers, 2014 to 2024). An irregularly shaped, elevated mark on the skin caused by deposits of excessive amounts of collagen during wound healing. "The central deep keloid region showed the more exaggerated keloid phenotype with respect to increased contraction, increased epidermal thickness, reduced HGF secretion and reduced collagen type IV α2 chain dermal gene expression." (PMID 32528951, 2020). "With respect to contraction, α-SMA immunoreactivity, HGF secretion and collagen type IV α2 gene expression, the surrounding normal skin showed intermediate between truly unaffected normal skin and keloid scar." (PMID 32528951, 2020). "Secretion of anti-fibrotic HGF and extracellular matrix collagen IV gene expression was reduced in the central deep keloid compared to normal skin." (PMID 30370495, 2018). "Increased expression of growth factors and cytokines such as CTGF, HGF and its receptor c-Met, VEGF and PLGF have been demonstrated in keloid-derived keratinocytes." (PMID 32528951, 2020). "We also examined secretion of a previously established wound healing mediator panel (CCL2, IL-6, CXCL8, VEGF, HGF and CCL27), which showed reduced HGF secretion in the reconstructed keloid model compared to the normal skin model." (PMID 31187196, 2019). "sNskin was usually intermediate between normal skin and keloid in the expression of scar parameters and often similar to the peripheral keloid model (contraction; α-SMA expression; secretion of HGF; expression of COL4A2)." (PMID 30370495, 2018). "Both the previously published baseline keloid model, as well as the central deep keloid model, showed increased contraction and α-SMA expression, decreased secretion of HGF, as well as decreased dermal expression of collagen type IV compared to Nskin." (PMID 30370495, 2018). "1α,25(OH)2D3 activates the HGF gene promoter and induces HGF expression and secretion in rat NRK-49F renal interstitial fibroblasts and in human keloid fibroblasts." (PMID 24600406, 2014). "Compared with in vitro reconstructed normal skin, the keloid model showed a trend of increased dermal thickness, increased α-SMA and p16 expression, reduced HGF secretion and reduced collagen type IV α2 chain, hyaluronan synthase 1 and matrix metalloproteinase 3 gene expression." (PMID 32528951, 2020). "In addition, the HGF inhibition of collagen synthesis and promotion of MMP production has shown promise for therapeutic applications in reducing the pro-fibrotic activity of keloid fibroblasts in vitro and in a keloid heterograft mouse model." (PMID 34439762, 2021). "Additionally, in contrast with the previously published basic keloid scar model (cultured without monocytes), we did not see decreased HGF secretion." (PMID 31187196, 2019).
lymph node metastasis (8 papers, 2019 to 2025). "Additionally, the role of HGF and c-Met in lymphangiogenesis might contribute to its influence during the formation of lymph node metastases." (PMID 31817278, 2019). "Nevertheless, HGF mRNA levels were not correlated with the age of the patient, tumor size, grade, lymph node metastasis, receptor status, and molecular subtype in this analysis." (PMID 39302921, 2024).
malignant mesothelioma (8 papers, 1998 to 2023). A malignant neoplasm of the pleura or peritoneum, arising from mesothelial cells. "Because HGF/SF was previously found in the pleural effusion fluids of patients with malignant mesothelioma and in paraffin-embedded tumour tissues, it is concluded that HGF/SF may well stimulate the growth and spread of malignant mesothelioma in vivo by paracrine and/or autocrine mechanisms." (PMID 9569039, 1998). "Another issue regards the hepatocyte growth factor (HGF)/scatter factor and its receptor tyrosine kinase, MET, which are highly expressed in most human malignant mesotheliomas." (PMID 36834912, 2023). "Here we show that Malignant mesothelioma patients have significantly higher level of Galectin-1, Mesothelin, Osteopontin, VEGF, shed SDC-1, MMP-7, HGF, NRG1-β1 and TIMP-1 compared to benign patients." (PMID 32731396, 2020). "In malignant mesothelioma cases, shed SDC-1 expression was significantly and positively correlated with HGF (p = 0.02; r = 0.3) and NRG1-b1 (p = 0.001; r = 0.4)." (PMID 32731396, 2020). "In about one half of the malignant mesothelioma cell lines analyzed, ERK5 activation appeared to be dependent on hepatocyte growth factor (HGF)-mediated activation of phosphoinositide 3-kinase (PI3K) and MEK5." (PMID 30901834, 2019). "Hepatocyte growth factor (HGF) and its receptor c-met are also known to activate ERK5 and upregulate one of the downstream targets fos-related antigen-1 (FRA-1) via PI3K-AKT signaling in malignant mesotheliomas (MMs)." (PMID 33572742, 2021). "Additionally, using the Proteome Profiler Array, we identified that other angiogenesis-related proteins including HGF, TGF-β1, FGF-4, NRG1-β1 are significantly upregulated in malignant mesothelioma cells, suggesting that these proteins may also have a prognostic and angiogenic role in MPM." (PMID 33562126, 2021).